PHGDH (phosphoglycerate dehydrogenase)
Diseases named in the same sentence as PHGDH in open-access papers (continued):
Sharing a sentence is not in itself a finding about the gene and the disease.
melanoma (continued). "However, this does not rule out a role for this transcription factor in concert with PHGDH to effect melanoma progression in our animal model." (PMID 32477466, 2020). "PHGDH amplification may alter glucose metabolism in human melanoma, and may result in changes in redox status, energy metabolism, and potentially, other signaling functions." (PMID 32664979, 2020). "Regardless of the mechanism resulting in aberrant melanin accumulation in hair follicles when PHGDH is expressed, this data illustrates that PHGDH can impact normal melanocyte biology and may contribute to why this gene is amplified in melanoma." (PMID 31331318, 2019). "Melanoma cell lines with amplified PHGDH had increased flux through the serine pathway." (PMID 24743024, 2014). "It has also been found that the gene encoding PHGDH (D-3-phosphoglycerate dehydrogenase from human), which controls flux from glycolysis into the serine biosynthesis pathway, is a possible oncogene and PHGDH amplification is most commonly found in human melanoma." (PMID 24733054, 2014). "Our western blot analysis confirmed increased expression of CYP27A1, which was upregulated in the bile acid metabolic pathway, and three additional glycolytic genes (PKM2, PHGDH, and PCK2) in melanoma CD8+ TILs compared to PBMCs." (PMID 38023136, 2023). "The combination of metabolic pathway-related kinase, such as phosphoglycerate dehydrogenase (PHGDH) and pyruvate dehydrogenase kinase (PDK), and MEK inhibitors also inhibited the growth of NRASmut melanoma cells." (PMID 36551302, 2022). "The first enzyme of this pathway, phosphoglycerate dehydrogenase (PHGDH) is overexpressed in many types of cancers such as breast, lung and melanoma." (PMID 33915900, 2021). "PHGDH is upregulated in melanoma at baseline, and is also upregulated in MEK inhibitor-resistant melanomas." (PMID 33511334, 2020). "In response to vemurafenib treatments of a vemurafenib-resistant melanoma cell line, SK-MEL-28VR1 established from parental BRAF V600E SK-MEL-28 cells, PHGDH was elevated to support cell proliferation by supplying nucleotides." (PMID 32226297, 2020). "Of note, we also checked cBioPortal and found that these proteins related to angiogenesis (i.e. FASN, CLIC4, HSPB1, ARHGEF1, PHGDH, MYO1C, CAV1) are altered in a total of 242 melanoma patients out of a total of 471 (51.36%)." (PMID 31142788, 2019). "The gene for the first enzyme of the pathway, phosphoglycerate dehydrogenase (PHGDH), has been shown to be focally amplified in some triple-negative breast cancers and melanomas." (PMID 31096630, 2019). "Phosphoglycerate dehydrogenase (PHGDH), the enzyme that catalyzes the first step in the serine–glycine biosynthesis pathway, is amplified in human melanoma and ER-negative breast cancer." (PMID 29911072, 2018). "Key enzymes such as D-3-Phosphoglycerate dehydrogenase (PHGDH), phosphoserine aminotransferase 1 (PSAT1), and phosphoserine phosphatase (PSPH) are upregulated in melanoma, enhancing nucleotide synthesis, methylation reactions, and antioxidant defense via glutathione production." (PMID 40573249, 2025). "Phosphoglycerate dehydrogenase (PHGDH), the first enzyme, which diverts glucose-derived carbon into de novo serine synthesis pathway, was found to be amplified and overexpressed in melanoma, indicating its clinically relevant potential." (PMID 33091721, 2020).
melanoma (continued). "The phosphoglycerate dehydrogenase (PHGDH) gene, which catalyzes the oxidation of 3-phosphoglycerate to 3-phosphohydroxypyruvate, is amplified in a subset of human tumors including triple negative breast cancer and melanoma." (PMID 27391339, 2016). "Moreover, 3-phosphoglycerate dehydrogenase (PHGDH), a key metabolic enzyme of SSP, was reported to amplify in melanoma and triple-negative breast cancer." (PMID 27356757, 2016). "The serine biosynthesis pathway, which involves the enzymes phosphoglycerate dehydrogenase (PHGDH), phosphoserine aminotransferase 1 (PSAT1), and phosphoserine phosphatase (PSPH), is frequently upregulated in malignancies such as triple-negative breast cancer and melanoma." (PMID 40535116, 2025). "To date, it has been reported that the level of PHGDH protein is increased in 16% of all cancers 32, 40% of melanoma samples 4, 70% of estrogen receptor (ER)-negative and triple-negative breast cancer samples, and even associated with subtypes of breast cancers." (PMID 32226297, 2020).
hepatocellular carcinoma (37 papers, 2013 to 2026). A malignant tumor that arises from hepatocytes. "In other studies, PHGDH enzyme augmentation was associated with resistance to a therapeutic agent in non-small cell lung cancer (NSCLC) and in hepatocellular carcinoma (HCC)." (PMID 38791048, 2024). "Recent studies have demonstrated the involvement of PHGDH in the development of various cancers, including esophageal cancer, colorectal cancer, and hepatocellular carcinoma." (PMID 39223162, 2024). "Recent studies have revealed that in hepatocellular carcinoma, PHGDH has been found to increase histone methylation levels and facilitate the transition from glycolysis to serine biosynthesis, thereby accelerating the development of hepatocellular carcinoma." (PMID 38994199, 2024). "HHT restrains tumor progression by inhibiting some oncoproteins in various malignancies, such as EphB4 in hepatocellular carcinoma, PHGDH in neuroblastoma, and NF-κB in acute myelogenous leukemia." (PMID 38770133, 2024). "The connection between serine metabolism and cancer was first suggested when it was observed that the activity of phosphoglycerate dehydrogenase (PHGDH) in passaged rat hepatoma cell lines was higher than that in normal rat liver cells." (PMID 37187454, 2023). "NRF2 SUMOylation promotes the elimination of ROS in cells by increasing the transcription of glutathione peroxidase 2 (Gpx2), which leads to the upregulation of PHGDH in hepatocellular carcinoma (HCC) cells." (PMID 37147729, 2023). "Kinesin family member 15 (KIF15) promotes the CSC phenotype and malignancy by means of PHGDH-mediated ROS imbalance in hepatocellular carcinoma." (PMID 36213825, 2022). "Consistently, a previous report found that phosphoglycerate dehydrogenase (PHGDH) is an important contributor for drug resistance in hepatocellular carcinoma." (PMID 34546848, 2021). "And inactivating PHGDH can promote ROS production and thus trigger apoptosis of hepatocellular carcinoma cells by drug treatment, like sorafenib." (PMID 34546848, 2021). "Early research showing increased PHGDH activity in rat hepatomas and colon carcinoma compared to matched healthy tissue pointed towards the importance of PHGDH activity in cancer." (PMID 29568346, 2018). "Specifically, enzymatic activity of PHGDH assayed in four transplantable hepatomas (Morris series: 7794B, 7793, 9121, and 5123TC) was elevated 1.7–10.6 times relative to control livers in rats of the same strain." (PMID 25574168, 2014). "PRMT1-mediated phosphoglycerate dehydrogenase methylation can promote serine accumulation in hepatocellular carcinoma, and can enhance glycolysis in hepatocellular carcinoma cells and promote the progression of liver cancer by methylating thymidine kinase and remodeling the actin cytoskeleton." (PMID 38402202, 2024). "Similarly, PHGDH can promote growth and proliferation of hepatoma cells by activating mitochondrial translation and respiratory metabolism through noncanonical functions." (PMID 38577610, 2024). "Although some evidence supported that PHGDH enhanced proliferation, migration and invasion of pancreatic cancer, and contributed to the resistance of sorafenib and other tyrosine kinase inhibitors in hepatocellular carcinoma." (PMID 33808696, 2021). "Similarly, resistance to tyrosine kinase inhibitors (TKIs) in hepatocellular carcinoma and EGFR mutation-positive lung adenocarcinomas was counteracted by PHGDH knockdown." (PMID 33397437, 2021). "Moreover, a recent study showed that linc01564 increased the expression levels of PHGDH by sequestering miR-107/103a-3p in hepatocellular carcinoma." (PMID 34957102, 2021). "Two years later, Snell and Weber published a paper entitled “Enzymatic Imbalance in Serine Metabolism in Rat Hepatomas” which showed that the activity of PHGDH was indeed increased in tissues with high cell-renewal capacity in addition to elevations in neonatal and regenerating liver cells." (PMID 25574168, 2014).
hepatocellular carcinoma (continued). "We recently demonstrated protein arginine methyltransferase 1 (PRMT1) is upregulated in hepatocellular carcinoma (HCC) to methylate and activate phosphoglycerate dehydrogenase (PHGDH), thereby promoting serine synthesis." (PMID 38839752, 2024). "Meanwhile, linc01564 can promote hepatocellular carcinoma cell proliferation (HCC) survival under glucose deprivation condition by regulating PHGDH expression in mRNA and protein levels." (PMID 37127605, 2023). "Beyond lung cancer, NRF2 SUMOylation in hepatocellular carcinoma (HCC) was shown to promote de novo serine synthesis via PHGDH upregulation, leading to serine accumulation and contributing to HCC maintenance." (PMID 33080927, 2020). "In hepatocellular carcinoma, ATAD2 modulates the expression of kinesin family member 15, which interacts with phosphoglycerate dehydrogenase to prevent its proteasomal degradation." (PMID 41158756, 2026). "Specifically, the level of serine in hepatocellular carcinoma (HCC) tissues is increased, whereas the expression of phosphoglycerate dehydrogenase (PHGDH), the first rate-limiting enzyme in serine biosynthesis pathway, is markedly downregulated." (PMID 36823188, 2023). "C-MYC directly controls the transcription of PHGDH, PSAT1, PSPH, SHMT1, and SHMT2 in human hepatoma and HeLa cells." (PMID 37949226, 2023). "To determine the association of the PPP and SGS pathways in clinical HCC, we analysed PHGDH, PSAT1 and G6PD RNA expression in HCC tumour and non-tumour liver tissue from the Cancer Genome Atlas (TCGA) liver hepatocellular carcinoma (LIHC) database." (PMID 33028928, 2020). "In studies of Hepatocellular Carcinoma (HCC), SUMOylation enhances the ability of NRF2 to scavenge ROS and upregulate PHGDH, promoting de novo serine synthesis." (PMID 40258841, 2025).
glioma (34 papers, 2013 to 2026). A benign or malignant brain and spinal cord tumor that arises from glial cells (astrocytes, oligodendrocytes, ependymal cells). "Collectively, these findings highlight the elevated expression of PHGDH in GSCs and its association with advanced progression in glioma." (PMID 40102981, 2025). "PHGDH expression is significantly elevated in GSCs, associated with aggressive glioma progression and poor clinical outcomes." (PMID 40102981, 2025). "In gliomas 35 and cervical 36, pancreatic 37, and colorectal cancer 38, the overexpression of PHGDH is associated with advanced TNM stage, large tumor, higher tumor grade, and shorter overall survival time, respectively." (PMID 32226297, 2020). "Examples include cystathionine accumulation in 1p/19q-codeleted gliomas indicating compartmentalized serine flux, and PHGDH-mediated vascular dysregulation underscoring stroma-tumor metabolic interdependence." (PMID 41486146, 2026). "In gliomas, PHGDH interacts with the oncogenic transcription factor FOXM1 to promote glioma cell proliferation and invasion." (PMID 41415540, 2025). "Studies have found that PHGDH increases the expression level of VEGF to enhance the progression of glioma brain tumors." (PMID 37187454, 2023). "Phosphoglycerate dehydrogenase (PHGDH) contributes to glioma progression through a direct interaction and stabilization of FOXM1." (PMID 34439090, 2021). "Since then, seminal publications confirmed the importance of PHGDH in cancer (triple negative ER breast cancer, glioma, pancreatic cancer, etc.) and notably demonstrated that PHGDH extinction led to a significant reduction in tumor proliferation." (PMID 33477510, 2021). "In gliomas, PHGDH expression, the first and rate-limiting step to divert substrates from glycolysis to serine production, was increased while PHGDH silencing reduced proliferation and invasiveness in GBM cells." (PMID 34588983, 2021). "Patient survival (5-year) within grade III and IV groups was 43.3% in the low-PHGDH expression group compared with 18.5% in the high-PHGDH expression group (p < 0.001), underscoring PHGDH as a prognostic marker for glioma." (PMID 32477466, 2020). "Our results affirm that high PHGDH levels protect GBM cells under most adverse conditions of the glioma microenvironment by maintaining redox homeostasis." (PMID 32203214, 2020). "A possible oncogenic role has also been attributed to PHGDH (phosphoglycerate dehydrogenase), involved in the synthesis of serine, pyruvate, and hydroxypyruvate, in breast and skin cancers and glioma." (PMID 33008042, 2020). "In glioma, PHGDH identified as directly upstream of FOXM1 prevents FOXM1, a proverbial oncogene, from proteasome degradation due to ubiquitination by interacting with its N-terminal, which facilitates tumor proliferation, invasion, and tumorigenicity." (PMID 32226297, 2020). "In glioma, PHGDH interacts with and stabilizes the oncogenic transcription factor FOXM1 to promote the proliferation, invasion and tumorigenicity of glioma cells." (PMID 30744688, 2019). "The oncogenic transcription factor FOXM1 was also downregulated in PHGDH shRNA-silenced glioma cells." (PMID 25574168, 2014). "Mechanistic investigations revealed that inhibition of PHGDH expression in glioma cells impaired proliferation, invasion, and tumorigenicity in vitro and in vivo." (PMID 25574168, 2014). "Kaplan–Meier curves indicated that in WHO grade I and II glioma patients, the 5-year survival was 82.3 % in the low-PHGDH expression group compared with 64.5 % in the high-PHGDH expression group (p < 0.001)." (PMID 23229761, 2013). "To explore PHGDH expression in gliomas, we performed immunohistochemical analysis on 132 paraffin-embedded glioma specimens ranging from WHO grade I to grade IV." (PMID 23229761, 2013). "Inhibition of PHGDH in glioma cells significantly decreased cell proliferation, invasion and tumorigenicity." (PMID 23229761, 2013).
glioma (continued). "PHGDH mRNA and protein was barely detectable in the NHA, whereas PHGDH mRNA and protein expression levels increased to different levels in the glioma cell lines." (PMID 23229761, 2013). "Recent study suggests that PHGDH expression level is high in astrocytic tumors and inhibition of PHGDH in glioma cells significantly decreased cell proliferation, invasion and tumorigenicity." (PMID 24318446, 2013). "To exclude the possibility that high PHGDH expression levels were due to cell types other than the astrocytomas, we analyzed PHGDH mRNA and protein expression levels in glioma cell lines and compared them with normal human astrocytes (NHA)." (PMID 23229761, 2013). "Next, we used Q-PCR to detect PHGDH mRNA expression levels in detect the PHGDH mRNA expression of 40 glioma tissues (10 grade I astrocytomas, 10 grade II astrocytomas, 10 anaplastic astrocytomas and 10 glioblastomas) and 10 normal brain tissues." (PMID 23229761, 2013). "In the statistical analyses, we determined that PHGDH expression levels highly correlated with the clinicopathological grade of the glioma samples (p < 0.0001)." (PMID 23229761, 2013). "After PHGDH inhibition, the U87 and U251 glioma cells exhibited a massive G2 arrest compared with the control cells." (PMID 23229761, 2013). "Mechanistic investigations revealed that deprivation of PHGDH in glioma cells impaired proliferation and invasiveness." (PMID 23229761, 2013). "Furthermore, IHC analysis of a glioma tissue microarray indicated that higher PHGDH levels in high-grade gliomas compared to low-grade ones, and patients with high PHGDH IHC scores were more prone to recurrence and had lower survival rates." (PMID 40102981, 2025). "PHGDH is overexpressed in glioma and affects invasion and angiogenesis." (PMID 32762776, 2020). "Moreover, we identified PHGDH as a potential prognostic marker for glioma patient cumulative survival." (PMID 23229761, 2013). "Next, we examined whether PHGDH inhibition could impact glioma cell invasion using transwell chambers." (PMID 23229761, 2013). "However, the expression patterns of PHGDH in glioma and its molecular functions (aside from being a metabolic enzyme) have not yet been reported." (PMID 23229761, 2013). "From these data, we concluded that PHGDH could stabilize FOXM1 protein from degradation in glioma cells." (PMID 23229761, 2013). "In conclusion, we report that PHGDH is a novel prognostic marker in glioma patients." (PMID 23229761, 2013). "Therefore, the histone and DNA methylation status in 2-HG over-producing cancers could be either enzyme (IDH, PHGDH, or else) or cancer tissue type (triple-negative vs. ER-positive or leukemia vs. glioma or else)-dependent." (PMID 34436421, 2021). "PHGDH may be used as a potential prognostic marker for glioma patient cumulative survival." (PMID 24318446, 2013). "This interaction stabilized FOXM1 protein levels and sequentially induced the expression of a series of oncogenes, such as MMP-2, VEGF, Chk2 and cyclin D1, which suggests that in addition to metabolic functions, PHGDH may have other biological roles in glioma tumorigenesis." (PMID 23229761, 2013). "In gliomas, PHGDH expression levels positively correlate with WHO grade, and inhibiting PHGDH significantly decreases GBM cell proliferation and invasiveness." (PMID 40102981, 2025). "The results of immunohistochemical (IHC) staining showed that PHGDH, PSAT1, and PSPH expression levels in both low-grade gliomas and high-grade gliomas (GBM) are much higher than those in normal human brain tissue." (PMID 38098117, 2023). "Hypoxia-induced expression of phosphoglycerate dehydrogenase (PHGDH) and the mitochondrial serine hydroxymethyltransferase (SHMT2) was observed in three of five tested glioma cell lines." (PMID 32203214, 2020). "PHGDH interacted with and stabilized FOXM1 at the protein level, promoting the proliferation, invasion and tumorigenicity of glioma cells." (PMID 23229761, 2013).